CD4 (CD4 molecule)
Diseases named in the same sentence as CD4 in open-access papers (continued):
Sharing a sentence is not in itself a finding about the gene and the disease.
tumor (continued). "Thus, the median scores for CD4+, CD8+, and Treg cells were significantly higher in BCCs and SCCs than in NS, while they were identical between the two tumor types." (PMID 38891095, 2024). "In addition, TIL density takes into account other cell subtypes (CD4+, FOXP3) besides CD8+, thus providing a more comprehensive description of the conditions and immune interactions in the tumor microenvironment that contribute to the overall results." (PMID 38638854, 2024). "Therefore, the presence of Tregs inhibits the activation and function of CD4+ CD38+ T cells, CD8+ T cells and M1 macrophages and consequently promotes tumor progression." (PMID 38674427, 2024). "To characterize the role of DPT cells in T cell‐mediated anti‐tumor immunity in vivo, we transplanted CD8+ T cells purified from OT1 mice into immunodeficient mice with B16F10‐OVA tumors and then eliminated DPT cells by anti‐CD4 treatment." (PMID 39225354, 2024). "Our findings revealed higher proportions of CD4+ T cells, dendritic cells (DCs), macrophages, stromal cells, and regulatory cells (Tregs) in non-response tumor tissues." (PMID 38948071, 2024). "This is plausible since CD4+ T cells of this phenotype have an oligoclonal repertoire and lie on a trajectory that culminates in CD39 expression, which is defined as a marker of tumor-antigen reactivity." (PMID 38383773, 2024). "We also find that trNK may also recruit CD4+ Tregs via IL-16 but concomitant FAS signaling would lead to Treg apoptosis and support tumor control." (PMID 39656086, 2024). "In vivo, Ascomylactam C enhances CD4+ and CD8+ T cell infiltration in tumor tissues." (PMID 39438986, 2024). "MIHC staining revealed that SPP1 was substantially colocalized with CD68+ cells but barely colocalized with CD4+ T cells, CD8+ T cells or B cells and that SPP1 was more highly expressed in macrophages derived from HNSCC tumor tissues compared with those derived from adjacent normal tissues." (PMID 39726047, 2024). "Moreover, mDCN and/or mCD40L armed oncolytic adenoviruses altered the immune state to activate anti-tumor responses, including increasing CD8+ T effector cells and CD4+ memory T cells, reducing MDSCs and Tregs in peripheral blood." (PMID 39306655, 2024). "As the inclusion of CD4 helper antigens improved CD8+ T cell responses both quantitatively and qualitatively, we compared the vaccines for their ability to induce protective anti-tumor immunity." (PMID 39040850, 2024). "Additionally, CD4+ T cells, activated by MHC class II on APCs, support CD8+ T cells, recruit immune cells and secrete cytokine to anti-tumor cells." (PMID 39204053, 2024). "Effector CD4 T cell have been increasingly recognized for anti-tumor activity, independent of their helper function." (PMID 38474178, 2024). "Meanwhile, IL17A+CD4+ T cells in tumour tissue were of less interest, and there is no data representing the effect of these cells, depending on their compartment of tumour tissue." (PMID 39409156, 2024). "Notably, there was an upregulation of tumor-infiltrating NK cells and CD8 + T cells in mice treated with both CD73 and CD155 mAbs compared to the PBS control, and a downregulation of CD4 + T cells." (PMID 38429294, 2024). "Moreover, the subpopulations of CD4+ T cells have many functions and mechanisms in the TIME, which are playing the anti-tumor or pro-tumor role." (PMID 39735340, 2024). "Recently, CCL19/21 have been shown to induce the migration of CD4+ T cells to non-lymphoid tissue, especially to the nervous system, to preserve the balance between immune surveillance (against tumor and pathogens) and tolerance." (PMID 38330029, 2024). "However, C1 exhibited increased levels of anti-tumour components in TME, including CD8 + T cells, activated memory CD4 + T cells, T follicular helper cells, M1 macrophages, and activated dendritic cells." (PMID 39030559, 2024).
tumor (continued). "There was a 3- to 4-fold increase in the number of tumor-infiltrating CD4+ and CD8+ T cells in Tnfr1−/− mice, which was not demonstrably increased by the addition of anti-PD-1." (PMID 39178856, 2024). "Given that CD4+ cells are primarily hijacked by MDV to promote disease development and tumour formation, other populations of T cells, such as CD8+ and γδ T cells, may play crucial roles in the immune response to MDV infection." (PMID 38879650, 2024). "In addition, IRFs were positively correlated with the abundance of tumor-infiltrating immune cells, including B cells, CD8+ T cells, CD4+ T cells, macrophages, neutrophils, and dendritic cells in PC." (PMID 39457004, 2024). "Moreover, multicolor immunofluorescence staining of CD4 and CD8 antibodies was further performed in tumor tissue to assess the infiltration of T cells into the tumor immune microenvironment." (PMID 38280084, 2024). "In addition, Suzanne I.S. Mosely and colleagues have demonstrated that NK (26.92%), CD4+ T (7.24%), and CD8+ T (5.04%) are indeed higher in immunotherapy-sensitive CT26-derived tumor models compared to others, including LL/2." (PMID 38953994, 2024). "We aimed to perform an immunohistochemical characterization of a panel of immune biomarkers (CD3, CD4, CD8, CD163, programmed death ligand 1 and programmed death 1) of 30 GBM patients to determine the tumor immune infiltrate and the distribution of the principal immunological markers." (PMID 39594814, 2024). "Tumor segments in Type 2 OC (HGSC) were shown to have stronger infiltration of immune cells, including CD3, CD4, CD11c, CD163, CD56 and CD80, suggesting that both pro- and anti-inflammatory immune phenotypes are elevated inside the tumor nests compared to Type 1 OC." (PMID 39026018, 2024). "Furthermore, considering that ECN can act as an immune adjuvant to recruit immune cells to infiltrate tumor sites, CD3+, CD4+, and CD8+ immune cells accumulate in the tumor microenvironment, reversing tumor immune suppression." (PMID 38919710, 2024). "Furthermore, it enhances the maturation of T helper cells into the CD4+CD25+Foxp3+Treg pathways, which can inhibit effector T cell responses and thus reduce anti-tumour immunity." (PMID 39120301, 2024). "IL-10, a crucial immunoregulatory cytokine secreted by various lymphoid and myeloid cells, including Th2, CD4, CD8 T cells, NK cells, macrophages, and dendritic cells, can be produced by tumor cells themselves, acting as a cytokine synthesis inhibitory factor (CSIF) leading to immunosuppression." (PMID 39118076, 2024). "In addition, stroma-restricted CD8/CD4 T cells supply IFNγ and TNF/IL1 to the tumor nest, which further promotes tumor NOS2/COX2 expression at the tumor margin that leads to the formation of metastatic and CSC niches that are regionally distinct." (PMID 39356141, 2024). "Currently, the CD4+ T lymphocytes have been studied with more attention in cancer immunotherapy due to their ability to promote CD8+ T activation and act directly or indirectly against tumor cells." (PMID 39599846, 2024). "We have also shown a prevalent infiltration of CD39+ CD4+ T cells in central and peripheral tissues compared with non-tumor tissues." (PMID 38335302, 2024). "Likewise, a subset of CD4 cells, Th17 cells, have stem-like properties, and when redirected to express a CAR, they can lead to tumor regression in preclinical models." (PMID 39199630, 2024). "The abundance of progenitor CD8+T cells and DC cells in tumours was similar between patients who responded to immunotherapy and those who did not, but there was significant enrichment of CD4+ helper T cells in patients who were effective." (PMID 39816386, 2024). "The infiltration of CD4+ and CD8+ T cells was markedly increased in CT26-iPSC-Vac tumor tissue." (PMID 38821980, 2024). "We also note that 4-1BB is exclusively expressed among Foxp3+ CD4 Tregs in tumor-bearing mice, is absent among other T cell subsets, and is entirely absent in naïve mouse T cells." (PMID 38932362, 2024).
tumor (continued). "The strong potential of these classes of inhibitors was demonstrated in preclinical models of colorectal cancer treated in vivo with nanoparticles loaded with the STAT3 inhibitor BBI608, which resulted in enhanced infiltration of CD4+ and CD8+ TILs at tumor sites and tumor regression." (PMID 39281678, 2024). "The results demonstrated a positive correlation between PTK6 and Tregs, as well as a negative correlation with CD8+ and CD4+ T cells across most tumor types." (PMID 38573548, 2024). "The recruitment of NK cells by CD4+ T cells to mediate anti-tumor response is MHCI independent, suggesting multiple co-ordinated anti-tumor immune responses activated as a result of Yap1 depletion in the tumor epithelium." (PMID 37957015, 2024). "Consistently, antibody-mediated T cell depletion confirmed the relevance of CD8+ but not CD4+ T cells for immune control of PGE2-producing BRAFV600E tumours in Cd4crePtger2−/−Ptger4fl/fl mice." (PMID 38658748, 2024). "In recent years, CAR-T technology has been used to modify CD4+ T cells, and anti-tumor ability does not depend on cytotoxicity, but indirectly acts on tumor cells through the production of interferon-γ (IFN-γ), a large area and a long distance." (PMID 38327747, 2024). "However, depletion of CD4+ T and CD8+ T cells negatively affected the ability of VVL-GL21 to control tumor growth and survival, demonstrating that the anti-tumor effects of VVL-GL21 in this model are primarily mediated by CD8+ T, CD4+ T, and NK cells." (PMID 39830516, 2024). "In our study, MTV and TLG showed significant negative correlations with CD4 + cell infiltration and significant positive correlations with tumor grade." (PMID 38627864, 2024). "As an initial evaluation of the effects of AZD6738 and radiation on the immune response, we also investigated the infiltration of various immune populations, including CD4+ and CD8+ T cells, dendritic cells (CD11b+CD11c+), and macrophages (CD11b+F480+) into the tumor." (PMID 39235982, 2024). "We orthotopically implanted mammary PyMT tumors into wild-type (WT) and hCD4 antigen knock-in (hCD4-KI) mice to further explore endogenous CD4+ cells in the tumor, spleen, draining and nondraining lymph nodes (dLNs and ndLNs)." (PMID 39239511, 2024). "CD8 + cytotoxic T lymphocytes (CTL), CD4 + T cells, NK cells and NKT cells all play critical roles in tumor immunity, while humoral immunity may not only inhibit tumor growth but also enhance it." (PMID 38218960, 2024). "Further, PD-L1 and PD1 expression are upregulated in tumor infiltrating CD8+ and CD4+." (PMID 39682081, 2024). "In addition, we analyzed other TME indicators (MDSCs, neutrophils, inflammatory monocytes, CD4+ T cells, and CD8+ T cells) in the peritoneal cavity of the tumor-bearing mice to understand the immune changes." (PMID 38303927, 2024). "Antitumor-related immune cells such as M1 macrophages, activated memory CD4 T cells, and resting dendritic cells demonstrated a strong positive correlation with RCD scores, whereas classical tumor-promoting immune cells like M2 macrophages were negatively associated with RCD levels." (PMID 38538696, 2024). "The presence of other tumor-associated immune cells in the tumor microenvironment, along with the secretion of inducible factors by this population of immune cells, leads to the aggregation of CD4+ CD25+ Tregs, which play a crucial role in promoting tumor progression." (PMID 38426090, 2024). "Indeed, monocytes from the CTT group, but not from the CTT with anti-Ly6G group, significantly upregulated the expression of IFN-γ in CD4+ T-cells, CD8+ T-cells and NK cells compared with monocytes from tumor-bearing mice." (PMID 39555061, 2024). "To investigate the distribution of LOY cells in CD4 + T lymphocytes we collected three public scRNAseq datasets containing fluorescence-activated cell sorted (FACS) T lymphocytes from cancer patients, with samples taken from tumour, healthy tissue and blood." (PMID 38443832, 2024).
tumor (continued). "Altogether, HLJD increased tumor infiltration of DCs, CD4+T and CD8+T cells in tumor." (PMID 38605368, 2024). "In addition, we observed an increased proportion of CD4 effector cells in the spleen of JIMT-1 and MDA-MB-231 mice, as well as in the tumor of JIMT-1 HTM upon irradiation combined with anti-PD-L1 treatment." (PMID 38742103, 2024). "Furthermore, we observed the presence of tertiary lymphoid structures within the tumor from mice treated with “BC@Z-M + L”, characterized by a distinct CD20+ B cell adjacent to a CD4+ and CD8+ T cell zone." (PMID 39613774, 2024). "The Clo treatment alone could slightly increase the infiltration ratio of CD4+ and CD8+ T cells in the tumor tissue, but CD4+ and CD8+ T cells decreased in the eBMDM+HS group following Clo treatment as compared with the same group without Clo treatment." (PMID 38491004, 2024). "Additionally, DCs in the TME secrete chemokines and cytokines that play a crucial role in recruiting and activating effector CD4+ and cytotoxic CD8+ T cells for effective anti-tumor immune responses." (PMID 38533507, 2024). "However, when tumor cells lack MHC class II molecules, CD4+ T cells will play a role by secreting various cytokines or assisting other immune cells." (PMID 39493763, 2024). "Stimulation by BiTE promotes the expression of CD69 and IL2RA, known as T-cell activation markers, on the vast majority of CD8 and CD4 T-cells, thus allowing all CD8 and CD4 T-cell subpopulations except the naive T cells to be involved in redirected tumor cell lysis." (PMID 38672662, 2024). "SLC31A1 expression has a substantial link with tumor purity, and it is markedly positively correlated with infiltrating levels of B lymphocytes, CD8 + T cells, CD4 + T cells, macrophages, neutrophils, and dendritic cells in BC, based on the “Gene of TIMER” module study." (PMID 39448672, 2024). "CD4+ T cells are essential for effective anti-tumor immunity, as evidenced in experimental studies where the absence of CD4+ T helper cells led to diminished functionality of CD8+ lymphocytes." (PMID 39600880, 2024). "Considering MHC-II mediates CD4+ T-cell epitope-initiated immune responses, we hypothesized that combining PCSK9 inhibitors with long peptide vaccines may achieve synergistic anti-tumor effects." (PMID 38600469, 2024). "CD4+ T cells and PDAC cancer cells must upregulate the very-long-chain acyl-CoA dehydrogenase (VLCAD) enzyme to acclimatize to the lipid-rich microenvironment of the tumor." (PMID 38434964, 2024). "HDL can induce cholesterol depletion in TAMs, thereby weakening their tumor-promoting effects, enhancing the anti-inflammatory effects of neutrophils, promoting the activation of CD8+ and CD4+ T cells, and regulating the function of antigen-presenting cells and their complements." (PMID 39253716, 2024). "Conversely, the constitutive absence of CD11chi DCs enhanced the proportion of CD4+Foxp3+RORγt+ Treg cells in lymphoid tissues under homeostatic and tumor-bearing conditions." (PMID 39206204, 2024). "In contrast, we observed a significant but positive correlation between the frequency of CD45+Dectin-1+ cells and CD3+ and CD8+ T cells but not CD4+ T cells in the CT26 tumour model." (PMID 38668817, 2024). "The GSE120280 dataset includes CD4+GFP+ Tregs and CD4+GFP- Resting conventional T cell (Tconv) populations, with spleen and tumor samples harvested and processed into single cells from tumor-bearing mice and the spleens of normal mice." (PMID 39273290, 2024). "Th1 subtype of CD4+T cells directly destroy tumor cells by secreting IFN-γ and TNF, whereas Th2 subtype secretes anti-inflammatory mediators such as IL4, which suppress immunity and support tumor growth." (PMID 39350256, 2024). "DOX and CpG release via MMP-9 enzyme in TME could increase tumor-specific antigen (TSA) releasing and recruitment of CD8 + and CD4 + T cells to both tumor environments and spleen, repressing tumor development, and improving animal survival." (PMID 38951806, 2024).
tumor (continued). "In vitro, OX40 gets upregulated on CD4+ and CD8+ TILs when exposed to autologous tumour cells." (PMID 38440738, 2024). "It recruits effector CD4+ and CD8+ T cells to the tumor microenvironment." (PMID 38928238, 2024). "The percentage of CD4+ TCR-T subsets in mice peripheral blood was higher in IL-21R-TCR-T 7 and 14 days after transfer, indicating that the IL-21R promoted the persistence of CD4+ TCR-T, which led to the increased amounts of tumor-infiltrating CD4+ TCR-T cells." (PMID 38643203, 2024). "Consequently, the induction of polyclonal T cells and decreased regulatory T cells (Tregs, CD4+CD25+FoxP3+), enhance the scope and strength of anti‐tumor immune responses." (PMID 39118566, 2024). "Our analysis showed that LINC01614 expression was correlated with the microenvironment score, hematopoietic stem cells, B cells, CD4+ T cells, CD8+ T cells, neutrophils, macrophages, and dendritic cells in 31 cancers, suggesting that LINC01614 influences tumor immune cell infiltration." (PMID 38655053, 2024). "Moreover, spatial transcriptomic data revealed that the infiltration score and the number of CD4+ and CD8+ T cells in CD45+ enriched‐ tumor/margin regions were significantly higher in BCG‐treated mice compared with untreated ones." (PMID 38308164, 2024). "Transduction of fusion-type IGKV3-20 by mDCs efficiently induces CD4+ and CD8+ CTL responses, and these CTLs are able to kill autologous mother cells expressing IGKV3-20 or pulsed IGKV3-20-synthesized peptides or HLA-matched IGKV3-20-positive tumor cell lines." (PMID 38370407, 2024). "Our findings suggested that MMP11 was positively correlated with macrophages M0 and negatively related to macrophages M1, NK cells activated, NK cells resting, T cells CD4 memory activated, and T cells follicular helper, indicating the remarkable interactions between MMP11 and tumor immunology." (PMID 39239548, 2024). "In addition, CD4+ and CD8+ PD-L1-CAR-T cells exhibited strong cytotoxicity when targeting PD-L1-high tumour cells." (PMID 38475858, 2024). "Exosomes prepared from ovalbumin (OVA)‐pulsed, activated DC were modified with anti‐CTLA‐4 antibody (EXO–OVA–mAb), which increased the migration of CD4 and CD8 T cells to the tumor site and increased the ratio of CTLs/Tregs in the microenvironment of the B16 melanoma tumor model." (PMID 39015555, 2024). "MHC-II interacts with CD4+ T-cells, which drive anti-tumor responses, mostly (although not always) through regulation, making them more likely to be involved in early tumor detection." (PMID 38515744, 2024). "The syngeneic mouse tumor models confirmed that galectin 7 reduces the percentage of CD4+ T cells in WT mice but not in PD-1 KO mice, suggesting a potential role of galectin 7 in PD-1." (PMID 38503797, 2024). "In advanced immunotherapy applications, double-negative T cells (DNTs) have shown robust resistance and safety against tumor cells in in vitro studies due to their lack of CD4 and CD8 expression." (PMID 38915099, 2024). "Depletion of CD8+ T cells, but not CD4+ T cells, with antibodies abrogated the antitumor effect of UA, suggesting that the UA‐enhanced anti‐tumor response is CD8+ T cell‐dependent." (PMID 38447147, 2024). "The presence of CD8+ T cells, CD4+ T cells, and other lymphocytes in the same cellular neighborhoods were identified as one type of spatial architecture that restricted the proximity of CD8+ T cells to tumor cells and heralded a poor prognosis." (PMID 38611111, 2024). "While knockout of ZFP36 somewhat increased antigen-independent activation in CD4 CAR-T cells and cytokine secretion, ZFP36-KO cells performed similarly to unedited mock cells in a xenograft tumor model and exhibited similar cytotoxicity, proliferation, and cytokine responses in antigen settings." (PMID 38326511, 2024). "We also found that cryoablation of the primary tumor could significantly increase the expression of PD-1 on CD8+T cells and CD4+ T cells in the secondary tumors." (PMID 39489086, 2024).